IFIT1 (interferon induced protein with tetratricopeptide repeats 1)
Diseases named in the same sentence as IFIT1 in open-access papers (continued):
Sharing a sentence is not in itself a finding about the gene and the disease.
viral infection (continued). "Likewise, the ISG response as determined by measuring IFIT1 mRNA expression, was similar or lower between HC1 and CAN1 COs under mock or virus infection conditions." (PMID 40894642, 2025). "Moreover, previous studies have implicatedsimilar ISGs, including OASL, IFI27, IFIT1 and IFI44L, in the pathogenesis of other viral infections such as hepatitis C virus (HCV),suggesting a broader role for these genes in viral-induced liver diseases." (PMID 40322700, 2025). "As there is cross-talk between the inflammasome and interferon-stimulated network in viral infections, we were not surprised to also see IFIT1, IFIH, and DDX58 anti-viral genes upregulated in COVID-19+ individuals." (PMID 38543837, 2024). "IFIT1 and IFIT2 (also known as ISG56 and ISG54, respectively) are interferon induced proteins primarily known for their roles in antiviral defense by restricting viral replication and modulating immune responses to combat viral infections." (PMID 39077737, 2024). "This trend follows for the other ISG transcripts analyzed, with ISG15 having an approximately 7.1-fold increase, IFIT1 an 11.7-fold increase, and OASL a 13.2-fold increase in transcripts in the C7/10-derived virus infection compared to the BHK-derived virus infection." (PMID 37632027, 2023). "No large differences in the up-regulation of IFIT1 or IFN-β gene expression were observed following pH1N1 virus infection when comparing lysates of apically infected AO at ALI or LMECs." (PMID 37072183, 2023). "Hence, IFIH1, TNFAIP3, IFIT1 and IFIT2 were the common immune response genes regulated by m6A during bacterial or viral infection, or LPS treatment." (PMID 35288544, 2022). "We observed that adult patients with epileptic seizures had peripheral whole blood that included miR-654-3p, miR-323a-3p, miR-323b, miR-3283p, miR-342-5p, miR-150-5p, miR-3395p and IFIT3, IFIT1, IFI44L, OAS3, and LY6E in the pathways connected to viral infection." (PMID 36172025, 2022). "Up-regulated differentially expressed genes (DEGs) indicated a clear relationship with the innate immune response against viral infection, including genes coding PRRs (LPG2 or DHX58) and IFN-stimulated genes (ISG15, Mx, STAT1, HERC5, IFI44, IFIT-1, NUP133, TRIM21)." (PMID 35215144, 2022). "More importantly, blockage of the cleavage (D126A) significantly increased the IFN-β promoter activity, mRNA levels of IFN-β and ISGs (IFIT-1 and MX1), and IFN-β production in the supernatants, especially at the late stage of virus infection and poly(I·C) treatment." (PMID 34125604, 2021). "Future works must therefore focus on the IFIT1–3 and IFI44 proteins, as well as on other yet identified proteins that induce chronic innate immune activation after viral infection and on the possibility that viral remnants contained in macrophages or other cell types, drive this process." (PMID 33081322, 2020). "Meanwhile, we found that IFNs could significantly trigger the production of a variety of IFN-induced genes (IFIT1, IFITM3, Mx-1, OASL, ISG15, PKR, GBP1, Viperin, BST2, IRF-1, and CXCL10) and MHC molecules, which play key roles in resistance to virus infection." (PMID 32655518, 2020). "IFIT (IFN-induced protein with tetratricopeptide repeats (TPRs))-family proteins contain four members in humans, namely IFIT1 (ISG56), IFIT2 (ISG54), IFIT3 (ISG60) and IFIT5 (ISG58), and are induced to high levels in response to IFN signaling and/or viral infections." (PMID 29215570, 2017). "Furthermore, because IRF-3 is degraded in A549/Npro cells, they cannot upregulate expression of IFIT1 in an IRF-3-dependent, IFN-independent manner in direct response to virus infection." (PMID 27512068, 2016). "Coherently, we found that viral infection induces the accumulation of an active form of CTNNB1 and that CTNNB1 gene silencing increases SeV-induced IFNB1, IFIT1 and TNF expression, as well as NFKBIA (IκBα) phosphorylation at serine 32 (P-Ser32) to release NF-κB inhibition." (PMID 23785285, 2013).
viral infection (continued). "IFIT-1, IFIT-2, IFIT-3, and IFIT-5, which were found to be the most down-regulated genes in LBW newborns, are induced in response to type I and type II IFNs against viral infections." (PMID 23626859, 2013). "The cell type-specific differences, however, were not due to variation in induction of Ifit1, as the gene was expressed highly in all cells after viral infection." (PMID 22589727, 2012). "Our results confirm and extend these observations by showing that the forced expression of IFIT1, IFIT2 or IFIT3 in human fibroblasts completely inhibited the replication of CHIKV and that the individual knock-down of each of these genes facilitated viral infection." (PMID 30959732, 2019). "Regarding upregulated DEGs, a clear relationship with the innate immune response against viral infection was observed, being unigenes detected those coding pattern recognition receptors (PRRs) (DHX58), and IFN-stimulated genes (ISG15, Mx, STAT1, HERC5, IFI44, IFIT-1, NUP133, and TRIM21)." (PMID 30065724, 2018). "IFIT1 restricts viral infection posttranscriptionally by blocking the translation of viral mRNA; therefore, we predicted that IFN-α–pretreated A549-ISG15−/− cells would remain susceptible to infection but that high levels of IFIT1 would mean these cells would not be permissive to PIV5 infection." (PMID 32423918, 2020). "The data showed that neither ISG15 nor IFIT1 were upregulated in HPV-positive placenta samples, probably illustrating that HPV was not in its active phase of viral infection at the time when samples were collected from patients." (PMID 28869524, 2017). "Despite its robust induction after viral infection or exposure of cells to type I IFN, Ifit1 did not contribute significantly to the control of wild type WNV infection in vivo." (PMID 22589727, 2012).
COVID-19 (44 papers, 2020 to 2025). A disease caused by infection with severe acute respiratory syndrome coronavirus 2. "For the variant allele effect, significant analyses were observed for the risk of severe COVID-19 development in PD-L1/rs17804441 SNP (allele variant C, OR = 1.92, CI 1.12–3.45, p = 0.045) and IFIT1/rs303215 (variant allele C, OR = 3.34, CI 1.55–7.20, p = 0.009) loci." (PMID 36992353, 2023). "The interferon-related genes IFNB1, ISG15, and IFIT1 were also activated in COVID-19 patients, and GO analysis showed that HERV-K (HML-2) can regulate the secretion of interferon." (PMID 35632738, 2022). "A significant decrease was observed for FI44L, MX1, RSAD2, ISIG15, and IFIT1 indicating a dysregulated type I/III interferon response in COVID-19 patients with pneumonia with a downregulation of ISGs." (PMID 34197543, 2021). "Consistently, genes (e.g., ISG15, IFITM1/2/3, OAS3 and IFIT1/2/3) associated with the IFN-response pathway, especially for IFN-I response, were significantly upregulated in COVID-19 associated acute necrotizing encephalopathy compared with healthy donors and other COVID-19 groups." (PMID 37848421, 2023). "Comparing the three groups of COVID-19 patients with each other, there was a trend to lower values for most ISGs in subjects with severe disturbances vs. subjects with mild symptoms, with a significant difference for IFIT1." (PMID 34299101, 2021). "Analysis of type I IFNs inducible genes expression performed in granulocytes and PBMCs showed increased transcription of ISG15 and IFIT1 mRNAs in cells of the COVID-19 patients, while ISG15 and IFIT1 mRNAs were detected in MIS-C at levels comparable to adult healthy controls." (PMID 33841438, 2021). "PBMCs displayed a generally low ex vivo and induced production of IFNα, although, surprisingly, their expression of ISG, particularly IFIT1, was high, in accordance with a study describing elevated expression of ISGs in bronchoalveolar lavage from COVID-19 patients." (PMID 33003471, 2020). "Patients with COVID-19 show a diminished type I Interferon signature in PBMCs, but neutrophils from these patients have an enhanced expression of interferon-related genes including IFNα, IFIT1 and ISG-15 which agrees with our finding of a higher amount of ISG-15 expressed in NETs." (PMID 34685525, 2021). "The increased expression of selected IFN-I (OAS1, OAS2, and IFIT1) and inflammasome related genes (CASP1, CASP5, NLRC5 and NAIP) between COVID-19 and HC PMNs was confirmed by RT-qPCR." (PMID 39172744, 2024). "In this study, the highest differentially expressed genes in COVID-19 (+) tissue, including ISG15 itself, IFIT1, RSAD2, OAS1, MX1, OASL, and IFIT3, are all important for the ISG15 pathway’s progression and are part of the lung tissue’s antiviral response." (PMID 38932146, 2024). "To further interrogate type I IFN signaling in critical COVID-19 patients, we quantified protein expression of interferon-stimulated genes (ISGs) MX1, IRF7, and IFIT1 by flow cytometry." (PMID 38231281, 2024). "As an indication of disease severity, we measured the mRNA expression levels of IFN-stimulated genes (IFIT1, IFIT3, ISG15, and MX2), pro-inflammatory cytokines (IL6, IL10), and chemokines (CXCL10, CCL2) that are correlated with COVID-19 exacerbation." (PMID 35562337, 2022). "Another study also reported increased interferon signaling genes including IFI44L, IFIT1, IFIT3 and ISG15, in CD16+ monocytes in COVID-19 cases compared to healthy controls." (PMID 34108966, 2021). "In our study, we report that IRF7, ISG15, IFI44L, IFIT1, and IFIT3 gene expression is increased in CD16+ monocytes from people with mild COVID-19 compared to healthy controls." (PMID 34108966, 2021). "OAS1, OAS2, OAS3, IFIT1, IFIT3, IFI44, IFI44L and IFITM1: Current COVID-19 genetic studies incline to analyze those genes together." (PMID 34109284, 2021).
COVID-19 (continued). "We found that COVID-19 neutrophils displayed higher basal level of IFNα, IFIT1, and ISG15 mRNA compared to COVID-19 PBMCs, healthy donor PBMCs, and healthy donor neutrophils." (PMID 33003471, 2020). "This pointed to a robust anti-viral response only in COVID-19 patients at D1 which was substantially muted by D7, as represented by the temporal expression patterns of key antiviral and interferon-related genes such as OAS2 and IFIT1." (PMID 37090709, 2023). "Genes associated with the IFN pathway, such as IFI27, IFIT1, IFIT2, OASL and OAS3, showed significantly higher expression levels, in particular individuals with long COVID-19 when compared to non-long COVID-19 and the organoid systems infected with the alpha variant." (PMID 40055791, 2025). "We observe an upregulation of genes involved in antiviral response pathways, including OAS1 that mediates RNase L pathway, IFIT1, and APOE at the upper respiratory airway of COVID-19-infected Ghanaians compared with a relevant publicly available dataset (GSE166530) from an Indian COVID-19 cohort." (PMID 38375062, 2024). "OASL, RSAD2, ISG20, IFI16, and IFIT1 were not previously annotated in the COVID-19 KEGG pathway." (PMID 38580667, 2024). "Our study found that the high expression of IFN-β in COVID-19 patients induced an increase in ISG15 and a high expression of IFIT1 (ISG56), the main subclass of ISG proteins with broad-spectrum antiviral activity, which may be the antiviral immune mechanism induced by SARS-CoV-2 infection." (PMID 35632738, 2022). "Furthermore, this CA dimension correlated with a subset of blood neutrophils that specifically expressed ISGs such as IFIT1, RSAD2, and OAS3 but also PD-L1, suggesting that a high-viral load in the lung can significantly influence the blood immune landscape in COVID-19 patients." (PMID 33674591, 2021). "Moreover, it was found that increasing IFIT1 and IFIT3 has been reported previously in CD16+ monocytes of mild and severe COVID-19 patients, while the IRF7 was not differentially expressed." (PMID 35422859, 2022). "In line with the single-cell study, signs of an interferon response were observed irrespective of disease severity (IFIT1, IFIT3), while only severe COVID-19 patients’ granulocytes featured expression of genes with suppressive functionality, such as ARG1 or CD274 (PD-L1)." (PMID 33441124, 2021).
ZIKV infection (21 papers, 2017 to 2025). "Thus, we hypothesized that differences in the basal antiviral state, as indicated by IFIT1 expression, may partially account for the differential susceptibility of LC and SC to ZIKV infection." (PMID 31311882, 2019). "Immunoblot assay with anti-IFIT1 or ISG15 antibody confirmed the upregulation of ISG expression during ZIKV infection." (PMID 39178324, 2024). "While MX1 and IFIT1 were the top upregulated proteins in SC following ZIKV infection, a major highlight of this study was that these proteins were also shown to restrict ZIKV replication in SC." (PMID 34079533, 2021). "Our data collectively suggest that MX1 and IFIT1 are potent markers of the antiviral state in SC in response to ZIKV infection." (PMID 34079533, 2021). "Our data demonstrated that interferon (IFN) signaling was the most significantly enriched pathway and the antiviral proteins MX1 and IFIT1 were among the top upregulated proteins in SC following ZIKV infection." (PMID 34079533, 2021). "Consistent with mRNA data, immunofluorescence staining detected markedly higher levels of IFIT1 protein in mock-infected and infected LC compared to SC, despite the detection of robust ZIKV infection in SC." (PMID 31311882, 2019). "To probe this question further, we evaluated mRNA levels of IFIT1 in SC and LC following ZIKV infection." (PMID 31311882, 2019). "ZIKV infection was shown to induce the expression of the ISGs IFIT1-3, RSAD2/Viperin, and OAS1 in primary human DCs." (PMID 31652496, 2019). "For example, ZIKV infection of A549 cells has been associated with down-regulated expression of ISGs including ISG15, IFIT1, and IFIT2 in response to IFN-β treatment, as compared to mock infection." (PMID 31652496, 2019). "Interestingly, we observed nuclear localization of IFIT1 in mock-infected LC that was noticeably more distributed to the cytoplasm following ZIKV infection." (PMID 31311882, 2019). "Furthermore, also consistent with mRNA data at 24 h, IFIT1 protein was induced in SC by ZIKV infection at 48 h, yet the immunoreactivity of IFIT1 in infected SC was still much lower compared to LC." (PMID 31311882, 2019). "Furthermore, Huh-7 cells showed reduced expression of the ISGs Viperin/RSAD2 and IFIT1 during ZIKV infection, following poly(I:C) stimulation." (PMID 31652496, 2019). "Hence, we examined the ISGs transcript levels for DDX58, IFIT1, ISG15, and IFNB1, and analyzed the transcript levels of inflammatory cytokines including TNF-α and IL-6 that are associated with severe symptoms during ZIKV infection." (PMID 34745057, 2021). "Overall, these results provide additional insights into the response of LC to ZIKV infection; however, further investigation is warranted to carefully determine whether heightened basal expression of antiviral genes, including IFIT1, does indeed contribute to the resistance of LC to ZIKV infection." (PMID 31311882, 2019). "In contrast to Zika virus infection, exogenous IFNɛ strongly induced ISG15, OAS1, IFIT1, and IFI6 within 12 hours post-treatment." (PMID 39621805, 2024). "Type II IFN (IFNγ) are key inducers of proinflammatory cytokines such as IRF1, IFIT1, CXCL10 and crucially, known cellular receptors for ZIKV infection such as AXL, Tyro3, and DC-SIGN." (PMID 35536870, 2022). "The data in this study highlight IFN-I as a driver of the antiviral state that limits ZIKV infection in SC and suggests that MX1 and IFIT1 function as antiviral effectors against ZIKV in SC." (PMID 34079533, 2021). "Upon ZIKV infection, IFN-λ and the ISGs IFIT1 and Mx1 were selectively induced in the reconstituted cells, thus excluding off-target effects of the RIG-I KO." (PMID 33658344, 2021). "We found that increased levels of MX1 at the later time points of infection coincided with diminished ZIKV infection while the silencing of MX1 and IFIT1 enhanced peak ZIKV propagation in SC." (PMID 34079533, 2021).
ZIKV infection (continued). "Collectively, these data indicate that proteins involved in innate antiviral defense are the most prominent dysregulated proteins in SC during peak ZIKV infection, with MX1 and IFIT1 as the top upregulated proteins detected." (PMID 34079533, 2021). "Interferon-stimulated genes (ISG) such as MX2, IFIT1, IFIT3, IFITM1, IFI35, and RSAD2 (Viperin) were significantly upregulated after ZIKV infection." (PMID 30781519, 2019). "ZIKV infection induced increased SC expression of IL-6, interferon (IFN)β1, IFN-λ, IFIT-1, TNFα and IL-23A mRNAs as well as IFN-λ receptors and negative regulators of IFN signaling." (PMID 31289325, 2019). "As expected, mRNA for viperin, IFIT1 and IFN-β significantly increased following polyI:C stimulation, however this was significantly attenuated in the presence of ZIKV infection." (PMID 28667332, 2017). "In contrast, JEG3 choriocarcinoma cells were more responsive to infection with increases, albeit moderate, in mRNA expression for IFIT1 and IFN-β at 24 and 48 h.p.i, however viperin expression was attenuated at both time points post ZIKV infection." (PMID 28667332, 2017). "The dynamic between IFN response and ZIKV infection kinetics in SC remains unclear, therefore we further determined whether MX1 and IFIT1 serve as antiviral effectors against ZIKV." (PMID 34079533, 2021). "These included MX1, IFIT1, ISG15, SAMHD1, IFIT3, and STAT1, all of which have been shown to be similarly upregulated by ZIKV infection in other human cell types, including fibroblasts and pluripotent stem cell (iPSC)-derived neural progenitor cells (NPC), as also demonstrated by LC-MS/MS analysis." (PMID 34079533, 2021). "Furthermore, ZIKV infection of A549 (human lung carcinoma) cells resulted in enhanced expression of IFN-β and several ISGs (e.g., MX1, IFIT1, and IFI44), compared to mock infection." (PMID 31652496, 2019). "The IFNβ and its downstream ISGs, including IFIT1 and IFIT2, were induced by ZIKV infection." (PMID 28373913, 2017). "Furthermore, both IFN-β treatment and ZIKV infection induced the expression of MX1 and IFIT1." (PMID 34079533, 2021). "Interestingly, although IFIT1 levels did not further increase following ZIKV infection, immunostaining detected apparent nuclear localization of IFIT1 in addition to diffused staining in the cytoplasm of infected LC." (PMID 31311882, 2019). "During ZIKV infection we observed a reduction of IFNL1, IFIT1, and IFIT2, but not IFNB, IFIT3, and ISG15 transcription in the absence of DNA-PKcs." (PMID 36311766, 2022). "To investigate this further we quantified viperin, IFIT1 and IFN-β mRNA following polyI:C stimulation of Huh-7 cells in the presence or absence of ZIKV infection." (PMID 28667332, 2017).